BRAF (B-Raf proto-oncogene, serine/threonine kinase)
Diseases named in the same sentence as BRAF in open-access papers (continued):
Sharing a sentence is not in itself a finding about the gene and the disease.
melanoma (continued). "BRAF, MEK, NRAS, HRAS, KRAS, c-KIT, c-Met, VEGFR, PTEN, and PIK3CA mutations are common in melanoma." (PMID 34804979, 2021). "Malignant melanoma has been classified in four subgroups according to its main genetic drivers by The Cancer Genome Atlas: mutant BRAF, mutant NRAS, mutant NF1, or triple wild-type tumors." (PMID 34362135, 2021). "For example, there are two BRAF inhibitors, including vemurafenib and dabrafenib, as well as the two MEK1/2 inhibitors trametinib and cobimetinib, that have been approved for BRAF-mutant melanoma." (PMID 33801965, 2021). "In recent years, relevant improvement in the prognosis and survival of patients with melanoma has been achieved, since the introduction of BRAF/MEK tyrosine kinase inhibitors and immune checkpoint inhibitors." (PMID 34571969, 2021). "For example, while suppressing BRAF signaling in BRAF (V600E/K) mutant melanoma cells is effective, multiple resistance mechanisms have been reported to drive MAPK pathway reactivation." (PMID 34885161, 2021). "Although several recent studies have discussed long-term severe adverse events after this combined therapy, the treatment of BRAF V600 melanoma combined with these two drugs appears advantageous compared with alternative treatments." (PMID 34063139, 2021). "Oncogenic BRAF (that activates ERK1/2) is a prime target for cancer and dabrafenib was developed as a BRAF inhibitor for melanoma." (PMID 34296750, 2021). "Previous studies have demonstrated that resistant melanoma cells displayed activated ERK due to a MEK2 mutation and BRAF amplification, which contributed to sustained mTOR activity in resistant cells." (PMID 34304249, 2021). "The median overall survival for all patients with BRAF-positive melanoma for patients who received combined 2nd line TT and CKI therapy was 34.1 months from the onset of CKI treatment." (PMID 34743688, 2021). "Together, these data demonstrate that the sensitivity of BRAF-mutant melanoma cells to SP2509 and JIB-04 can be predicted based on their differentiation state (Ngfr versus Axl) and the relative levels of Znf217 and Kdm4b proteins." (PMID 33750776, 2021). "In BRAF-inhibitor resistant melanoma cells, we explored the role of FASN, an enzyme involved in lipogenesis overexpressed in metastatic melanoma." (PMID 34068792, 2021). "It has been reported that BRAF V600E MT is responsible for melanoma progression through activation of the downstream MEK/ERK pathway." (PMID 34069882, 2021). "In this article, we report our experience with targeted therapy rechallenging with BRAF and MEK inhibitors in patients with metastatic BRAF-mutated melanoma after progression with kinase inhibitors and immunotherapy." (PMID 34136385, 2021). "When the BRAFi, encorafenib was compared to vemurafenib with stage III and IV melanoma patients, the patients on either BRAF inhibitor had comparable PFS." (PMID 34066966, 2021). "Of note, the percentage of BRAF-positive melanomas in CheckMate 067 was 31.5%, which is lower than the reported prevalence of BRAF mutations among patients with melanoma (approximately 60%)." (PMID 34914610, 2021). "For example, Hirata and colleagues showed that the growth of melanoma cells on the fibronectin-coated surface resulted in their blunted response to the PLX4720—BRAF V600D/E inhibitor." (PMID 34440617, 2021). "This feedback leads to one important difference in response to treatment between melanoma and CRC: BRAF(V600E) inhibition causes a rapid feedback activation of EGFR, which supports continued proliferation." (PMID 33507915, 2021). "Preclinical studies in mouse models of BRAF V600E mutant melanoma have begun to elucidate the mechanistic basis for improved immunological responses to combined treatment with BRAF and MEK inhibitors." (PMID 33807608, 2021). "The combination of BRAF and MEK inhibitors provides robust clinical responses in patients with BRAF-mutated melanoma." (PMID 34149718, 2021).
melanoma (continued). "A subgroup of BRAFV600E‐driven melanomas acquires resistance to BRAF inhibitors by overexpressing this protein." (PMID 33955157, 2021). "On the basis of our analysis, we, therefore, anticipate that it is worth carrying out further exploration of novel pan-class BRAF inhibitors and performing further research focused on melanoma in order to override vemurafenib-resistance." (PMID 33917428, 2021). "Melanoma develops resistance to BRAF inhibitors (vemurafenib, dabrafenib) and MEK inhibitors (trametinib, cobimetinib)." (PMID 34570764, 2021). "An interesting study has identified resistance-related mutations in BRAF positive patients that initially achieved partial or complete response to BRAF inhibitors but whose melanoma later progressed." (PMID 34123788, 2021). "In this study, we sought to investigate the effect of HA15 on four BRAFV600E-mutant melanoma cell lines and their BRAF inhibitor-resistant counterparts established by our group." (PMID 33498201, 2021). "Vemurafenib and dabrafenib plus trametinib are highly selective small-molecule inhibitors that have antitumor effects against melanoma with mutant BRAF kinase in the MAPK pathway." (PMID 34201096, 2021). "In both BRAF-mutated and NRAS-mutated melanoma cell lines, CH5126766/RO5126766 were shown to arrest the cell cycle in G1; meanwhile, SK-MEL-2 xenografts demonstrated suppression of tumor growth." (PMID 33807778, 2021). "RAS is a non-BRAF oncogene activated in malignant melanoma and enhances tumor functions, such as cell growth and apoptosis." (PMID 34829495, 2021). "This was followed by the approval of vemurafenib, a BRAFV600 inhibitor, which lead to an improved overall survival in untreated BRAF mutant melanoma." (PMID 33562484, 2021). "This has been successfully translated to practice in the treatment of many cancers including EGFR-driven lung cancers, BRAF-driven melanomas, Bcr-abl driven leukemias, and many other types of cancer." (PMID 33907275, 2021). "BRAF-mutant melanoma proliferates and survives primarily by activation of mitogen-activated protein kinase kinase (MEK)." (PMID 34206728, 2021). "A retrospective study of 217 patients confirmed that, compared to BRAF-mutant and -wild-type melanomas, NRAS-mutant tumors show a more aggressive biological behavior." (PMID 34209415, 2021). "For example, simvastatin, by inhibiting RAS or BRAF signaling, reversed vemurafenib resistance developed through activation of RAS or BRAF in mutant melanoma." (PMID 34065757, 2021). "For example, Ro-4987655, a highly selective mitogen-activated protein kinase kinase (MEK) inhibitor, has proved its efficacy in BRAF V600 mutant melanoma, BRAF wild-type melanoma, and KRAS mutant NSCLC patients." (PMID 34603309, 2021). "Inhibitors of the MEK are frequently used in combination with BRAFi, markedly improving the survival of patients with BRAF-mutant tumors, and this combination is FDA approved for use in BRAFV600E-mutated melanoma." (PMID 35187538, 2021). "One study found this growth factor to be upregulated in melanoma cell lines resistant to BRAF and MEK inhibitors, activation of the FGFR cascade leads to sustained ERK function." (PMID 33807778, 2021). "Taken together, these findings illustrate that bilirubin reversed vemurafenib-induced proliferation suppression mainly by blocking apoptosis in BRAF V600 mutant melanoma cells." (PMID 34222023, 2021). "In turn, BRAF mutations are the dominating genetic causative factor in superficial spreading melanoma (SSM), whereas for ALM, typical mutations can be found in the BRAF, NRAS, KIT, and NF1 genes." (PMID 34575876, 2021).
melanoma (continued). "Here the authors show that BRN2 is a haplo-insufficient tumour suppressor that positively regulates PTEN expression and in the context of BRAF mutation and heterozygous PTEN, BRN2 loss promotes melanoma initiation and progression." (PMID 34140478, 2021). "The blue-white veil is also a dermoscopic feature of BRAF and NRAS mutated melanomas and carriers of genetic variants in MTAP, as reported in different studies." (PMID 34440462, 2021). "In contrast, there was no significant decrease in cell viability in the NRASQ61L mutant (WM1366) or BRAF/NRAS wild-type (WM3211) melanoma cell line." (PMID 34885166, 2021). "Melanoma, a cancer originated from melanocytes, frequently presents mutations in the MAPK pathway, mainly in BRAF and NRAS proteins, at incidences up to 52% and 28%, respectively, according to The Cancer Genome Atlas Network." (PMID 34885944, 2021). "In this study, our retrospective analysis showed that bilirubin is a critical intrinsic factor that negatively correlates with the efficiency of vemurafenib in patients with BRAF mutant melanoma." (PMID 34222023, 2021). "Inhibition of mutated BRAF results in compensatory activation of MEK kinases, and, therefore, treatment of BRAF-mutated melanomas, always involves the combination of BRAF- and MEK-targeted drugs." (PMID 34681592, 2021). "BRAF gene was usually observed in distant metastatic melanomas with increased BRAF MAF value comparing to the primary tumor." (PMID 34885093, 2021). "The mentioned mutated genes as well as a number of involved epigenetic events occurring in melanoma cells contribute to the dysregulation of several signaling pathways comprising hyperactivated BRAF-MEK, PI3K/PTEN, or c-KIT cascades." (PMID 33440911, 2021). "Vemurafenib was the first BRAF inhibitor to be approved by the FDA for the treatment of advanced BRAF exon 15 V600E-mutant melanoma patients." (PMID 33801689, 2021). "In this retrospective study, we concluded that patients with stage III or IV BRAF mutant melanoma treated with 1L immunotherapy had significantly longer BMFS and OS compared with those treated with 1L targeted therapy." (PMID 34137219, 2021). "Next, the effect of EO05 in combination with dabrafenib and trametinib, the current standard treatment for BRAF mutant melanoma patients, was also assessed." (PMID 34059622, 2021). "The data suggest a 10% survival advantage for women, mainly seen in patients ≥60 years of age and patients with BRAF V600 mutant melanoma." (PMID 34572865, 2021). "To investigate mechanisms underlying BRAFi resistance in melanoma, we initially assessed SOX2 levels in BRAF-mutant melanoma." (PMID 33613844, 2021). "In summary, the possible mechanisms of resistance in melanoma to both solo BRAFi therapy and combinatory BRAF/MEK inhibitor treatment include a wide variety of parallel pathways, cell signaling, and transcription patterns." (PMID 33807778, 2021). "The number of high confidence miRNA-mRNA hybrids discovered in the three biological replicates of the BRAF-mutant melanoma cell line A375 (A1, A2, and A3) ranged between 50 and 95 K." (PMID 33806450, 2021). "Treatment options for patients with resected stage III melanoma include observation (i.e., monitoring and treating if the melanoma recurs), adjuvant immunotherapy, and those with BRAF mutant melanoma adjuvant BRAF-targeted therapy." (PMID 34507552, 2021). "This study sought to compare the clinical outcomes after RT between patients with BRAF+ and BRAF− melanoma." (PMID 34537078, 2021). "Our data showed that forced expression of PERK conferred resistance to BRAF inhibitor in the parental cell with inactivated PTEN human melanoma cells." (PMID 34282258, 2021). "For the treatment of BRAF-mutant melanoma, the drug instructions have clearly pointed out that vemurafenib can cause abnormal liver function." (PMID 34222023, 2021).
melanoma (continued). "And BRAF-V600 inhibitor can suppress the activation of TGF-β signaling via dephosporylation of TFEB, while TFEB phosphorylation and TGF-β upregulation play a pro-tumorigenic role in BRAF inhibitor resistant melanoma." (PMID 34247571, 2021). "The combination of a BRAF- with a MEK-inhibitor at their full dose (as in BRAFV600E/K mutant melanoma) has low cutaneous toxicity." (PMID 33921947, 2021). "The use of an inhibitor of Rho kinase (ROCK), which is modulated by RhoA, has been shown to resensitize melanoma cell lines to BRAF inhibitors." (PMID 33807778, 2021). "Trametinib was described to decrease the number of cells in the synthesis phase in BRAF-mutant lung cancer cells, and to induce G1 cell cycle arrest and apoptosis in RAS- and RAF-mutated melanoma cells." (PMID 33669371, 2021). "Vemurafenib and dabrafenib, selective oral tyrosine kinase inhibitors of the oncogenic BRAF V600 kinase, have been tested in BRAF mutant melanoma patients." (PMID 34359651, 2021). "Accordingly, loss-of-function mutations of the NF1 protein result in hyper-activation of RAS and, in combination with mutant BRAF protein, prevent oncogene-induced senescence during melanoma development by deregulating the PI3K and MAPK pathways." (PMID 34576054, 2021). "To identify the regulators of such variations, we use a library of 276 small-molecule epigenetic modulators in BRAF-mutant melanoma cell lines that cover a wide spectrum of differentiation states." (PMID 33750776, 2021). "In these lesions, BRAF p.V600E was detected in 51 patients, whereas 52 patients had BRAF-wt melanomas." (PMID 33915880, 2021). "For example, the BRAF fusion gene has been found in melanomas, prostate and gastric cancer, and in 85% of astrocytic pilomcytomas." (PMID 33474634, 2021). "SOX2 induction (mRNA and protein) was observed by mutant BRAF inhibitor vemurafenib treatment in melanoma." (PMID 33613844, 2021). "Three human melanoma cell lines (A375, D10, and NA8) with BRAF V600E mutation were kindlyprovided by Prof. Giulio Spagoli (University of Basel, Switzerland)." (PMID 34308569, 2021). "To this end, we herein describe the identification of novel kinase inhibitors possessing potent inhibitory activities against melanoma cells harboring class II (G464E) and class III (G469E, D594G) as well as class I (V600E) BRAF mutations." (PMID 33917428, 2021). "In the COMBI-i trial, the objective response rate of combined spartalizumab (anti-PD-1 inhibitor), dabrafenib, and trametinib was 78% in advanced BRAF-mutant melanoma, and 44% of patients achieved a complete response." (PMID 34804979, 2021). "Both PTEN loss and PIK3CA mutations have been shown to increase the rate of melanomagenesis induced by BRAF mutants in genetically-engineered mouse models, which indicates the potential importance of these genetic alterations in melanoma biology." (PMID 33549048, 2021). "It is well established that MAPK reactivation occurs in resistance to the combination of dabrafenib and trametinib in BRAF-mutant melanoma." (PMID 34831014, 2021). "A number of FDA-approved targeted therapies have become standard of care in BRAF mutant melanoma patients." (PMID 33921974, 2021). "BRAF, which is an oncogenic driver in mCRC patients, was already established as a therapeutic target structure in malignant melanoma many years ago." (PMID 34259881, 2021). "A study conducted sensitivity assays of growth inhibition and apoptosis induction for the RAF inhibitor (RAFi), vemurafenib, and the MEK inhibitor (MEKi), selumetinib, against a panel of 16 BRAF-mutant melanoma cell lines." (PMID 35008473, 2021).
melanoma (continued). "With 5-year follow-up, only 19% of patients treated with dabrafenib (BRAF V600E inhibitor) plus trametinib (a MEK inhibitor) continue to have ongoing responses of their melanoma despite continual therapy." (PMID 34743688, 2021). "BRAF inhibitor vemurafenib-treated melanoma cells was found to lead to transforming growth factor beta 1 (TGF-β1) release, which increases the deposition of fibronectin, type I collagen, α-smooth muscle actin ‘as well as CAFs." (PMID 34371697, 2021). "Previous studies suggested that co-targeting the AKT/mTOR pathway reversed the resistance of some melanoma cell lines with intrinsic cross-resistance to BRAF and MEK inhibitors." (PMID 34304249, 2021). "For melanoma patients whose tumors harbor mutation in NRAS, treatment with BRAF inhibitors is contraindicated." (PMID 34092233, 2021). "Other studies have shown that simultaneous inhibition of the MAPK, PI3Kβ/IGF1R, and PI3Kα pathways induced apoptosis and inhibited tumor growth in BRAF-mutant and loss-of-function PTEN melanoma models." (PMID 33807778, 2021). "The obtained results showed that the LNPs that encapsulate the combinations of the two tumor suppressor miRNAs are highly efficient in inhibiting the proliferation and viability of melanoma cells, and potentiate the efficacy of drugs that inhibit BRAF and MEK." (PMID 33546290, 2021). "This cell behavior led us to test the effects of a chemical inhibitor of DHCR24, U18666 A, on BRAF sensitivity in melanoma cells." (PMID 34068792, 2021). "Next, a QBDA melanoma panel was applied to 16 FFPE and 7 FF clinical tissue samples, and we found co-existence of BRAF V600E and low-frequency NRAS Q61K mutations in one FFPE tissue." (PMID 34675197, 2021). "Mechanistically up-regulated Notch signaling is involved in this process, and inhibition of Notch signaling can sensitize these melanomas to BRAF inhibitor." (PMID 33968932, 2021). "The JNK inhibitor JNK-IN-8, which reduces c-Jun phosphorylation, decreased melanoma cell migration and sensitized melanoma cells to BRAF inhibition." (PMID 34604096, 2021). "Activations of the mitogen-activated protein kinase (MAPK) pathway by BRAF and NRAS mutations are more common in low-CSD melanoma (60% and 20%, respectively)." (PMID 34440462, 2021). "The BRIM-8 trial investigated adjuvant vemurafenib monotherapy versus placebo in patients with completely resected BRAF V600-mutant melanoma, in either American Joint Committee on Cancer (AJCC) 7th edition stage IIC-IIIB (cohort 1) or stage IIIC (cohort 2)." (PMID 33801689, 2021). "Trametinib is reported to induce apoptosis at varying levels and, overall, it is less potent/efficacious in NRAS mutant melanoma cell lines compared to BRAF mutant melanoma cell lines." (PMID 33921974, 2021). "Currently, mutations in four different proteins (BRAF, GNAQ/GNA11, cKIT, NRAS) are well known to occur during melanoma formation, and affect the MAPK pathways by disrupting the healthy cells’ response to the emerging oncogenes." (PMID 33730175, 2021). "Adjuvant targeted therapy (TT) improves relapse free survival in patients with resected BRAF mutant stage III melanoma." (PMID 33087895, 2021). "Our results suggest that BRAF/MEK inhibition in melanoma patients allows an increased expansion of pre-existing melanoma-specific T cells by induction of T-bet and TCF7 in these." (PMID 33275172, 2021). "This approach is showcased by the study of BRAF inhibition in patients with melanomas and colorectal cancers who experience significant differences in sensitivity despite similar omics profiles." (PMID 33507915, 2021). "In melanoma, it was described that ITCH can directly interact with BRAF and promotes its lysine 27-linked polyubiquitination." (PMID 33800394, 2021). "CK2α was shown to decrease the efficacy of dabrafenib in BRAF-mutant melanoma cells via its kinase-independent scaffolding function." (PMID 33807778, 2021).